SLC5A5 (solute carrier family 5 member 5)
Description:
Sodium:iodide symporter that mediates the transport of iodide into the thyroid gland. Can also mediate the transport of chlorate, thiocynate, nitrate and selenocynate.
Synonyms: NIS; TDH1
Tractability: Antibody: UniProt places it where antibodies can reach, with high confidence; its Gene Ontology location is reachable by antibodies, with high confidence; UniProt predicts a signal peptide or a membrane-spanning region.
Safety:
Unwanted effects reported when the protein is acted on. In parentheses: how it was acted on, where the effect was seen, and who reports it.
Cognitive Function, Decreased (inhibition; source: AOP-Wiki)
Altered, Amphibian metamorphosis (inhibition; source: AOP-Wiki)
Impairment, Learning and memory (inhibition; source: AOP-Wiki)
Increase, Adenomas/carcinomas (follicular cell) (inhibition; source: AOP-Wiki)
Gene: Protein-coding gene on chromosome 19 (17,871,945 to 17,895,174, forward strand). Ensembl gene ENSG00000105641.
Subcellular location: Cell membrane; Cytoplasm
Pathways (Reactome):
Disease: Defective SLC5A5 causes thyroid dyshormonogenesis 1 (TDH1)
Metabolism: Thyroxine biosynthesis
Transport of small molecules: SLC-mediated transport of inorganic anions
Gene Ontology:
Molecular function: iodide transmembrane transporter activity; monoatomic anion:sodium symporter activity; protein binding; protein homodimerization activity; sodium:iodide symporter activity; organic acid:sodium symporter activity; solute:sodium symporter activity; transmembrane transporter activity
Biological process: cellular response to cAMP; cellular response to forskolin; cellular response to gonadotropin stimulus; cellular response to Thyroid stimulating hormone; iodide transmembrane transport; iodide transport; sodium ion transport; thyroid hormone generation; transmembrane transport; transport across blood-brain barrier; sodium ion transmembrane transport
Cellular component: cytoplasm; extracellular exosome; extracellular vesicle; nucleus; plasma membrane; membrane
Genetic constraint (gnomAD): Loss-of-function variants: 52 observed, 65.38 expected, observed/expected ratio (o/e) 0.8, 90% interval 0.64 to 1. The upper end of that interval is the gene's LOEUF score, 1, which puts it in group 4 of 6, group 1 being the genes least tolerant of losing a copy. Missense variants: 797 observed, 844.95 expected, observed/expected ratio (o/e) 0.94, 90% interval 0.89 to 1. Synonymous variants: 397 observed, 373.96 expected, observed/expected ratio (o/e) 1.06, 90% interval 0.98 to 1.15.
Homologues: Orthologues: chimpanzee SLC5A5 (99% identical), macaque SLC5A5 (98% identical), dog SLC5A5 (85% identical), pig SLC5A5 (85% identical), mouse Slc5a5 (81% identical), guinea pig SLC5A5 (77% identical), rat Slc5a5 (72% identical), tropical clawed frog slc5a5 (63% identical), zebrafish slc5a5 (56% identical), Drosophila melanogaster kumpel (29% identical), Drosophila melanogaster bumpel (29% identical), Drosophila melanogaster Smvt (29% identical), and 9 more. Paralogues in human: SLC5A8 (46% identical), SLC5A12 (43% identical), SLC5A6 (36% identical), SLC5A2 (21% identical), SLC5A11 (21% identical), SLC5A9 (20% identical), SLC5A4 (20% identical), SLC5A1 (20% identical), SLC5A10 (20% identical), SLC5A3 (18% identical), SLC5A7 (17% identical).
Diseases named in the same sentence as SLC5A5 in open-access papers:
SLC5A5 is named in the same sentence as 138 diseases in open-access papers, as found by Europe PMC text mining. Sharing a sentence is not in itself a finding about the gene and the disease. The quoted sentences say what the papers report.
thyroid cancer (249 papers, 2005 to 2026). "Although SLC5A5 is essential for iodine metabolism and thyroid control, the association between SLC5A5 and thyroid cancer remains complex and poorly understood." (PMID 40134821, 2025). "The SLC5A5 gene encodes the sodium–iodide symporter (NIS) protein, which is central in the transport of iodine into thyroid cells, and its frequently decreased expression and function in thyroid cancer limits the effectiveness of radioiodine." (PMID 37352166, 2023). "Another CTC-associated gene, SLC5A5, is often used to detect recurrent thyroid carcinomas, yet yields unsatisfactory results." (PMID 30781659, 2019). "We aimed to analyse the effect of selumetinib on the expression of sodium iodide symporter (NIS; SLC5A5) and associated miRNAs in thyroid cancer cells." (PMID 30018229, 2018). "Mutations in TIMM44 and NDUFA13 have been reported to be associated with tumorigenesis in the thyroid, and the SLC5A5 gene encodes sodium-iodide symporter protein, whose down-regulation is associated with thyroid carcinomas." (PMID 23724128, 2013). "In addition to the genes that showed consistent dysregulation, SLC5A5 (encoding NIS) was investigated separately due to its known association with thyroid cancer and iodine metabolism." (PMID 39982585, 2025). "Our findings suggest a possible association between additional TERT promoter mutations, alongside low TDS and SLC5A5 mRNA expression in NTRK-rearranged metastatic RAI-resistant thyroid cancers and the re-induction failure of RAI uptake following larotrectinib treatment." (PMID 38642578, 2024). "Additionally, analysis of publicly available datasets of thyroid carcinomas revealed that high LAT1 expression is associated with potentially untreatable PTC presenting reduced NIS/SLC5A5 transcription and with ATC." (PMID 30241549, 2018). "Finally, the finding of high SLC7A5 levels significantly co-occurring with low SLC5A5 transcripts might indicate that LAT1 is associated with aggressive forms of thyroid cancer like RAI refractory PTC." (PMID 30241549, 2018). "Loss-of-function mutations in the SLC5A5 gene, which encodes the NIS protein, are rare in thyroid cancer." (PMID 39982585, 2025). "In thyroid carcinomas, downregulation of SLC5A5 is correlated to poor differentiation, locoregional recurrence, and distant metastases." (PMID 39408960, 2024). "In this case, radiosensitivity in thyroid cancer can be reduced by targeting the influence of miR-221-3p on the solute carrier family 5 member 5 (NIS)." (PMID 35681658, 2022). "Radioactive iodine (RAI) is widely used in the treatment of advanced follicular cell-derived thyroid cancers, but downregulation of the sodium-iodide symporter gene (SLC5A5, more commonly known as NIS) leads to resistance or RAI-R disease." (PMID 29455653, 2018). "The sodium iodide symporter (NIS; SLC5A5) mediates the uptake of iodide into thyroid follicular cells allowing both diagnostic and therapeutic application of radioiodide in thyroid cancer patients." (PMID 28380420, 2017). "SLC5A5 gene expression is reduced in radioactive iodine-refractory thyroid carcinoma." (PMID 40134821, 2025). "Notably, the expression of PPFP in human thyroid cancer cell cultures modulates the regulation of thyroid-specific genes, including SLC5A5, TPO, TG, and TSHR, that are regulated through PAX8 to different levels." (PMID 39685621, 2024). "A literature search by using the terms including “Thyroid Neoplasm” OR "Thyroid Carcinoma" OR "Thyroid Cancer" AND "DNA Methylations” OR “hypermethylation" OR "CpG Island" AND “sodium iodide symporter” OR "SLC5A5" was conducted in PubMed/MEDLINE, Web of Science, and Scopus databases." (PMID 36221112, 2022). "Having this in mind, we addressed SLC5A5 expression by qPCR and NIS expression by IHC analysis, in a large series of primary thyroid carcinomas and looked for possible associations with some clinicopathological and molecular features, as well as to the response to RAI therapy and outcome." (PMID 29298843, 2018).
thyroid cancer (continued). "SLC5A5 was previously reported to be downregulated in thyroid carcinomas by us and others." (PMID 27329729, 2016). "SLC5A5 gene expression was increased in the PTC group and decreased in the iodine-refractory thyroid carcinoma group." (PMID 40134821, 2025). "For instance, the sodium/iodide symporter (NIS, SLC5A5) is responsible for the uptake of radioisotopes of iodide in thyroid cancers." (PMID 38399253, 2024). "A successful treatment for thyroid cancer is strictly correlated with an active Sodium Iodide Symporter (SLC5A5; NIS), which allows the retention of radioiodine in the tumor cells." (PMID 35396551, 2022). "A successful treatment for thyroid cancer is strictly correlated with an active Sodium Iodide Symporter (SLC5A5; NIS), which allows the retention of radioiodine in the tumor cells, leading to cell death." (PMID 29561759, 2018). "Due to the decreased expression of SLC5A5, some patients with differentiated thyroid cancer were not sensitive to radioiodine therapy." (PMID 34248843, 2021). "Many of these aggressive thyroid cancers do not concentrate radioactive iodide from the lack of the sodium/iodide symporter (SLC5A5), resulting in decreased survival." (PMID 28160550, 2017).
breast cancer (69 papers, 2006 to 2026). A primary or metastatic malignant neoplasm involving the breast. "Previous studies have shown that combining all-trans retinoic acid (ATRA) and hydrocortisone increases SLC5A5 protein levels and radioactive iodide uptake in MCF-7 human breast cancer cells." (PMID 40508009, 2025). "We and others have reported that RAC1 signaling potentiates the TSH-induced transcription of the NIS (SLC5A5) gene in non-transformed thyroid cells, and also in MCF7 breast cancer cells, in this case through the activation of p38 MAPK signaling." (PMID 34771624, 2021).
papillary thyroid cancer (38 papers, 2008 to 2026). "Decreased Slc5a5 gene expression is observed in patients with hypothyroidism and papillary thyroid cancer." (PMID 35897811, 2022). "In fact, papillary thyroid carcinomas (PTCs) harboring the BRAFV600E mutation present lower SLC5A5 mRNA and NIS protein expression as well as less targeting to the basolateral membrane compared to PTCs BRAFWT." (PMID 29298843, 2018). "In order to validate our data, we also studied SLC5A5 expression on 378 primary papillary thyroid carcinomas from The Cancer Genome Atlas (TCGA) database." (PMID 29298843, 2018). "Given the highly significant role of NIS (SLC5A5) in the physiology and the cancer pathogenesis process, this paper's objective is to provide a comprehensive assessment of the associations between the NIS (SLC5A5) gene and protein with papillary thyroid cancer." (PMID 30595693, 2018). "This is in concordance with a previous study reporting that tissue expression of SLC5A5 was not significantly different between benign and malignant nodules, when the major subtype of malignant nodule was papillary thyroid carcinomas." (PMID 30781659, 2019).
differentiated thyroid carcinoma (36 papers, 2008 to 2026). Differentiated thyroid carcinoma (DTC), also known as papillary or follicular thyroid carcinoma, is a slow-growing malignancy usually presenting in adults as an asymptomatic thyroid mass. "NIS, a protein encoded by the SLC5A5 gene, is crucial for thyroid physiology, and in the case of differentiated thyroid carcinomas, such as PTC, is essential to enable radioiodine therapy, which is an important part of adjuvant PTC treatment." (PMID 34199867, 2021). "In differentiated thyroid carcinoma, the expression and functional integrity of NA+/I− symporter (NIS/SLC5A5) are decisive for the ability of concentrating iodine." (PMID 36685893, 2022).
thyroid (36 papers, 2011 to 2025). "The first step of thyroid hormonogenesis consists of the uptake of iodide into thyroid follicular cells against an electrochemical gradient through the sodium-iodide symporter (NIS/SLC5A5)." (PMID 40149910, 2025). "Unexpectedly, our analysis did not uncover pathogenic variants in the SLC5A5 gene to account for the genetic basis of the thyroid disease." (PMID 36012511, 2022).
thyroid tumor (30 papers, 2005 to 2026). A benign or malignant neoplasm affecting the thyroid gland. "Previous studies reported a lower SLC5A5 expression in cases harboring BRAFV600E, and there is experimental evidence showing that BRAFV600E can impair SLC5A5 expression, nevertheless the impact of other relevant mutations found in thyroid tumors on SLC5A5 expression remained unknown." (PMID 29298843, 2018). "In fact, hypermethylation of SLC5A5 distal enhancer has been reported in thyroid tumors and treatment with the demethylating agent 5‐aza‐2′‐deoxycytidine improved NIS expression and radioiodine uptake in FTC cells, though ineffective in ATC cells." (PMID 41147659, 2026). "Overstimulation of mTORC2 results in reduced expression of the SLC5A5 gene that encodes NIS mRNA, whereas phosphorylated p-AktSer473 strongly influences the metastasis of cells in thyroid tumours." (PMID 38313845, 2023). "Given the differential capacity in iodide uptake between tumors with either high or low autophagy activity, we hypothesize that a relationship could exist between SLC5A5 expression on the cell surface of thyroid tumor cells and autophagy." (PMID 27105307, 2016). "Some studies have been demonstrating that MAPK and TGF-β1/Smad/FoxP3 are involved in the re-differentiation of thyroid tumors and in the re-expression of the sodium-iodine symporter (NIS, also known as solute carrier family 5 member 5 - SLC5A5) in non-oncocytic tumors." (PMID 34177813, 2021).
hypothyroidism (26 papers, 2010 to 2025). Abnormally low levels of thyroid hormone. "In conclusion, we report novel compound heterozygous missense SLC5A5 gene variants causing defective iodide accumulation, thus leading to congenital dyshormonogenic hypothyroidism." (PMID 39749016, 2024). "Biallelic loss-of-function variants in the NIS-coding SLC5A5 gene cause congenital dyshormonogenic hypothyroidism due to a defect in the accumulation of iodide, which is required for thyroid hormonogenesis." (PMID 39749016, 2024). "We report novel compound heterozygous missense SLC5A5 gene variants causing defective iodide accumulation, thus leading to congenital dyshormonogenic hypothyroidism." (PMID 39749016, 2024). "A murine study using a severe hypothyroidism model (low-iodine plus Slc5a5 knockout) found a protective effect against NAFLD/MASLD." (PMID 38182610, 2024). "Highlighting the importance of NIS in thyroid physiology, biallelic loss-of-function variants in the NIS-coding SLC5A5 gene cause defective iodide accumulation, thus leading to congenital dyshormonogenic hypothyroidism." (PMID 39749016, 2024). "Disruption of SLC5A5 function by perchlorate, a pervasive environmental contaminant, leads to human pathologies, especially hypothyroidism." (PMID 35899258, 2022).
congenital hypothyroidism (16 papers, 2010 to 2025). A thyroid hormone deficiency present from birth. "Together, these findings suggest that the p.L562M variant decreases NIS targeting to the plasma membrane, and consequently reduces NIS-mediated iodide transport, thereby expanding the spectrum of congenital hypothyroidism-causing SLC5A5 gene variants." (PMID 39749016, 2024). "Here, we explored the presence of pathogenic SLC5A5 gene variants in a cohort of five unrelated pediatric patients with dyshormonogenic congenital hypothyroidism suspected of having a congenital iodide transport defect." (PMID 35600585, 2022). "Congenital iodide transport defect is an uncommon autosomal recessive disorder caused by loss-of-function variants in the sodium iodide symporter (NIS)-coding SLC5A5 gene and leading to dyshormonogenic congenital hypothyroidism." (PMID 36012511, 2022). "We identified the first exonic synonymous SLC5A5 gene variant causing aberrant NIS pre-mRNA splicing, thus expanding the mutational landscape of the SLC5A5 gene leading to dyshormonogenic congenital hypothyroidism." (PMID 35600585, 2022). "Over thirty pathogenic variants in the NIS-coding SLC5A5 gene have been reported in patients with dyshormonogenic congenital hypothyroidism." (PMID 36012511, 2022). "In our study, mutations in SLC5A5 for congenital hypothyroidism were screened for in the cohort of 273 CH patients." (PMID 33815280, 2021). "Defects in the human sodium/iodide symporter (SLC5A5) gene have been reported to be one of the causes of congenital hypothyroidism (CH)." (PMID 33815280, 2021). "Herein, we report a novel compound heterozygous missense mutation G51fs/G421R of SLC5A5 gene in a pediatric patient diagnosed as congenital hypothyroidism from newborn screening." (PMID 33815280, 2021). "Mutations in the SLC5A5 gene, which encodes NIS, lead to congenital hypothyroidism (CH) due to an I− transport defect (ITD)." (PMID 28706256, 2017). "This database holds records of published variants (single‐nucleotide variants and indels) that have an impact on splicing of disease susceptibility genes (e.g., congenital hypothyroidism with SLC5A5 gene, hypofibrinogenemia with FGB gene)." (PMID 26913838, 2016). "Using targeted next-generation sequencing, we investigated the presence of pathogenic variants in the SLC5A5 gene in a study cohort of nine unrelated patients with permanent dyshormonogenic congenital hypothyroidism and that were suspected of having an iodide transport defect." (PMID 36012511, 2022). "Mutations in SLC5A5 are associated with congenital hypothyroidism." (PMID 34209805, 2021). "Our analysis did not reveal pathogenic variants in the coding region of the SLC5A5 gene in three out of four patients with permanent congenital hypothyroidism." (PMID 35600585, 2022). "The G51fs/G421R compound heterozygous mutation in SLC5A5 in a pediatric patient diagnosed with congenital hypothyroidism has not been reported before." (PMID 33815280, 2021). "Mutations in the SLC5A5 gene encoding NIS that result in a non-functional protein lead to congenital hypothyroidism due to I− transport defect (ITD)." (PMID 28706256, 2017). "We aimed to identify, and if so to functionally characterize, novel ITD-causing SLC5A5 gene variants in a cohort of five unrelated pediatric patients diagnosed with dyshormonogenic congenital hypothyroidism with minimal to absent 99mTc-pertechnetate accumulation in the thyroid gland." (PMID 35600585, 2022).
follicular thyroid cancer (10 papers, 2011 to 2025). "SLC5A5 was reported to be downregulated in papillary and follicular thyroid cancer and dysregulated in patients with neurotransmitter, endocrine and immune abnormalities." (PMID 33971621, 2021). "We assume that follicular carcinoma-derived CTCs in the blood show a lower expression of SLC5A5 per cell, leading to the obtained real-time RT-PCR results." (PMID 30781659, 2019). "In conclusion, the expression of SLC5A5 in CTCs from peripheral blood can differentiate follicular adenomas from follicular carcinomas." (PMID 30781659, 2019). "The expression of SLC5A5 in CTCs may preoperatively distinguish thyroid follicular adenomas from follicular carcinomas." (PMID 30781659, 2019). "However, it is supported by a previous study showing that tissue expression of SLC5A5 by follicular carcinomas is lower than that of adenomas." (PMID 30781659, 2019). "Among the tested genes, the expression of SLC5A5 and LGALS3 were validated in a larger number of patients (n = 64) and our results show that SLC5A5 expression differentiated follicular adenomas from follicular carcinomas (area under the curve (AUC) = 0.831)." (PMID 30781659, 2019). "SLC5A5 is also a widely studied thyroid-specific/abundant gene often used to detect CTCs; however, it has not been studied in patients with follicular thyroid cancer." (PMID 30781659, 2019). "The concept of lower expression of SLC5A5 in CTCs from those with follicular thyroid carcinomas than in that of those with adenomas (benign nodules) has not been described in the literature." (PMID 30781659, 2019).
lung cancer (8 papers, 2011 to 2025). A malignant neoplasm involving the lung. "Here we describe the development of an orthotopic lung cancer animal model which utilizes the human sodium iodide symporter gene (hNIS; SLC5A5) as an imaging reporter gene for the purpose of non-invasive, longitudinal tumor quantification." (PMID 28036366, 2016).